HS3ST1 (heparan sulfate-glucosamine 3-sulfotransferase 1)
Description:
Sulfotransferase that utilizes 3'-phospho-5'-adenylyl sulfate (PAPS) to catalyze the transfer of a sulfo group to position 3 of glucosamine residues in heparan. Catalyzes the rate limiting step in the biosynthesis of heparan sulfate (HSact). This modification is a crucial step in the biosynthesis of anticoagulant heparan sulfate as it completes the structure of the antithrombin pentasaccharide binding site.
Synonyms: 3OST; 3OST1
Tractability: Small molecule: a structure with a bound ligand is known; it has a binding pocket of medium quality. Antibody: UniProt predicts a signal peptide or a membrane-spanning region. PROTAC: ubiquitination databases record sites on it; its protein half-life has been measured.
Gene: Protein-coding gene on chromosome 4 (11,393,150 to 11,429,564, reverse strand). Ensembl gene ENSG00000002587.
Subcellular location: Golgi apparatus lumen
Subcellular location (Human Protein Atlas): Vesicles
Pathways (Reactome):
Metabolism: HS-GAG biosynthesis
Gene Ontology:
Molecular function: [heparan sulfate]-glucosamine 3-sulfotransferase activity; sulfotransferase activity
Biological process: glycosaminoglycan biosynthetic process; heparan sulfate proteoglycan biosynthetic process
Cellular component: Golgi lumen; Golgi apparatus
Genetic constraint (gnomAD): Loss-of-function variants: 8 observed, 20.36 expected, observed/expected ratio (o/e) 0.39, 90% interval 0.23 to 0.71. The upper end of that interval is the gene's LOEUF score, 0.71, which puts it in group 2 of 6, group 1 being the genes least tolerant of losing a copy. Missense variants: 436 observed, 441.4 expected, observed/expected ratio (o/e) 0.99, 90% interval 0.91 to 1.07. Synonymous variants: 205 observed, 196.71 expected, observed/expected ratio (o/e) 1.04, 90% interval 0.93 to 1.17.
Homologues: Orthologues: chimpanzee HS3ST1 (99% identical), macaque HS3ST1 (98% identical), rabbit HS3ST1 (93% identical), pig HS3ST1 (93% identical), dog HS3ST1 (91% identical), guinea pig HS3ST1 (90% identical), rat Hs3st1 (89% identical), mouse Hs3st1 (88% identical), tropical clawed frog hs3st1 (72% identical). Paralogues in human: HS3ST5 (50% identical), HS3ST3A1 (40% identical), HS3ST3B1 (39% identical), HS3ST2 (39% identical), HS3ST4 (39% identical), HS3ST6 (39% identical), NDST4 (33% identical), NDST3 (31% identical), NDST2 (30% identical), NDST1 (29% identical).
Diseases named in the same sentence as HS3ST1 in open-access papers:
HS3ST1 is named in the same sentence as 27 diseases in open-access papers, as found by Europe PMC text mining. Sharing a sentence is not in itself a finding about the gene and the disease. The quoted sentences say what the papers report.
prostate carcinoma (4 papers, 2020 to 2024). A carcinoma that arises from epithelial cells of the prostate gland. "The glycosylated protein HS3ST1 in ER-negative breast cancers contributes to tumor metastasis and is also a biological prognostic indicator of glioma, prostate cancer, and acute lymphocytic leukemia." (PMID 33312950, 2020).
astrocytoma (3 papers, 2017 to 2024). "Moreover, heparan sulfate-glucosamine 3-sulfotransferase 1 (HS3ST1) and calponin 3 (CNN3) are overexpressed in astrocytoma, and mutations in phosphatidylinositol-4,5-bisphosphate 3-kinase catalytic subunit alpha (PIK3CA), PDGFRA, and MYCN are generally associated with poorer prognosis in gliomas." (PMID 39062515, 2024). "Validation of 6 biomarkers with the highest importance score in TCGA and CGGA cohorts revealed that HS3ST1, and CNN3 were overexpressed in astrocytoma, while SLAIN1, ABTB2, TRIM67 and DRG2 were overexpressed in oligodendroglioma." (PMID 35287567, 2022).
bladder cancer (3 papers, 2021 to 2022). "Notably, the overexpression of HS3ST1 was associated with poor prognosis while acting as a hypoxia-related biomarker in bladder cancer." (PMID 35309336, 2022). "HS3ST1 was related to the NF-κB signaling pathway and selected to construct a prognostic signature for bladder cancer." (PMID 36452497, 2022). "In this study, we selected four hypoxia-related genes that were highly related to bladder cancer patients’ survival status, including ANXA2, GALK1, COL5A1, and HS3ST1, to construct a signature and this signature is independent of other clinical characteristics." (PMID 34026819, 2021).
acute lymphocytic leukemia (2 papers, 2020 to 2021). "HS3ST1 is a member of the heparan sulfate biosynthetic enzyme family and has been reported to be associated with the NF-kB signaling pathway in acute lymphocytic leukemia." (PMID 34026819, 2021).
colorectal cancer (2 papers, 2022 to 2023). A primary or metastatic malignant neoplasm that affects the colon or rectum. "Conditional deletion of HS3ST1 significantly inhibited tumor development in colorectal cancer." (PMID 37964257, 2023). "Additionally, HS3ST1 has been reported to play a major role in the development of colorectal cancer." (PMID 35309336, 2022). "Moreover, HS3ST1 and PD1 could be promising antigen-specific immunotherapy targets for colorectal cancer." (PMID 35309336, 2022).
pancreatic cancer (2 papers, 2015 to 2025). "HS3ST1 is upregulated in pancreatic cancer and is specifically expressed by malignant ductal-like cells." (PMID 40924474, 2025). "To elucidate whether the increased expression of HS3ST1 results in elevated expression of HSAT in pancreatic cancer, we stained a 140-patient tissue microarray (TMA) of treatment-naive, early-stage PDAC — stages I and II as defined by the American Joint Committee on Cancer (AJCC) 7th edition." (PMID 40924474, 2025). "The discovery of HSAT in pancreatic cancer is interesting because acinar cells that do not express HS3ST1 have been suggested to be one possible source of malignant ductal-like cells, although the exact cell of origin is still debated." (PMID 40924474, 2025).
endometrial cancer (1 paper, 2022). Primary or metastatic malignant neoplasm involving the endometrium (mucous membrane that lines the endometrial cavity). "The HS3ST1 gene was reported as a favorable prognostic marker for urothelial cancer, renal cancer, and endometrial cancer." (PMID 35039759, 2022).
Ewing sarcoma (1 paper, 2022). A small round cell tumor that lacks morphologic, immunohistochemical, and electron microscopic evidence of neuroectodermal differentiation. "Specifically, we found upregulation of enzymes involved in the catabolism of heparan sulfate proteoglycans (including SGSH, GNS, HS3ST4, HS3ST1, HS2ST1, and HS6ST1) in human Ewing sarcoma." (PMID 35285802, 2022).
HCMV infection (1 paper, 2021). "At high (5.0) as well as low (0.01) multiplicity of infection (MOI), MCMV growth was significantly reduced in the single Hs3st1 and Hs3st4 knockouts as well as in the double Hs3st1/4 knockouts, indicating that 3-O-sulfation of HS is important for HCMV infection." (PMID 34352038, 2021).
non-small cell lung carcinoma (1 paper, 2024). A group of at least three distinct histological types of lung cancer, including non-small cell squamous cell carcinoma, adenocarcinoma, and large cell carcinoma. "HS3ST1 has been found to promote tumor non-small-cell lung cancer progression by regulating SPOP/FADD/NF-κB pathway." (PMID 38173042, 2024).
psoriasis (1 paper, 2012). An autoimmune condition characterized by red, well-delineated plaques with silvery scales that are usually on the extensor surfaces and scalp. "Two up-regulated IDD genes (HS3ST-1 and PTPN22) were also present in the psoriasis inflammatory DC transcriptome, which contains DEGs between CD11c+CD11c− DCs versus CD11c+CD1+ DCs FACS-sorted from psoriasis lesions." (PMID 22957057, 2012).
systemic lupus erythematosus (1 paper, 2021). An autoimmune multi-organ disease typically associated with vasculopathy and autoantibody production. "The remaining variants rs56402156, rs7920721, and rs4351014 (in/near EPHA1, ECHDC3, and HS3ST1) have not been directly associated with other traits, although their associated genes were implicated in systemic lupus erythematosus (HS3ST1) and cancer (EPHA1, ECHDC3)." (PMID 34992629, 2021).
tumor (16 papers, 2016 to 2025). "Inactivation of HS3ST1 in the PDAC cells resulted in increased tumor colony number and caused a significant increase in lung weight compared with WT cells in both FC1242 and FC1245 cell lines." (PMID 40924474, 2025). "In mice, ILC2s in advanced CRC highly express Hs3st1 (encodes the effector product that catalyzes heparan sulfate biosynthesis) and Pdcd1 (encodes immune checkpoint PD-1); deficiency of PD1 or HS3ST1 in murine ILC2s can considerably inhibit CRC tumor proliferation." (PMID 35720302, 2022). "The experiments also showed that the switch between AR signaling and EGFR signaling is mediated by HS3ST1 in tumor formation and growth." (PMID 37463954, 2023). "Nonetheless, several genes significantly increase in tumors and impact patient survival (XYLT2, B3GAT3, EXT2) while HS3ST1 is decreased in tumor." (PMID 33585200, 2020). "These were initially assessed by an overrepresentation analysis designed to capture both significance and directionality of pathway dysregulation based on predicted transcription factor activity as derived from the difference in target gene expression between HS3ST1–/– and WT tumor cells." (PMID 40924474, 2025). "HS3ST1 might acts as a molecular biomarker for tumor diagnosis and prognosis." (PMID 34195087, 2021). "A recent study found that HS3ST1 levels are higher in NSCLC tumors vs the adjacent tissues and promotes tumor progression." (PMID 40155749, 2025). "To further illustrate this point, we performed staining for p-ERK in tumor slides from FC1245 orthotopic tumors and compared them with WT tumors, which showed a significantly increased ERK activation in HS3ST1–/– tumors." (PMID 40924474, 2025). "Thus, HS3ST1 expression, and by inference HSAT, appears to affect tumor cell survival and/or seeding in this model." (PMID 40924474, 2025). "Experiments are underway to examine whether similar results are observed in KPC mice lacking HS3ST1 and to examine how host expression of HS3ST1 affects orthotopic tumor formation." (PMID 40924474, 2025).
cancer (7 papers, 2014 to 2025). A tumor composed of atypical neoplastic, often pleomorphic cells that invade other tissues. "The HS3ST1 protein is a rate-limiting enzyme that is essential for heparan sulfate synthesis that is overexpressed and associated with various cancers, affecting proliferation and apoptosis." (PMID 38398086, 2024). "In the case that the cancer cells acquire resistance to ADT as CRPC, however, the expression of HS3ST1 and 3-OS HS is upregulated, facilitating the binding of EGF and HB-EGF to EGFR via 3-OS HS." (PMID 37463954, 2023). "Transcriptional patterns of HS-metabolic enzymes (EXT1, EXT2, NDST1, NDST2, GLCE, 3OST1/HS3ST1, SULF1, SULF2, HPSE) were determined in normal, benign, and cancer human prostate tissues and cell lines (PNT2, LNCaP, PC3, DU145)." (PMID 24782989, 2014). "Interestingly, inactivation of HS3ST1 led to a total reduction of HSAT in the tissues as well as in the murine KPC cancer cells, suggesting that although multiple enzymes can generate HSAT, HS3ST1 is the primary enzyme responsible for HSAT expression in vivo." (PMID 40924474, 2025).
infection (2 papers, 2011 to 2021). The state of being infected such as from the introduction of a foreign agent such as serum, vaccine, antigenic substance or organism. "Several sulfotransferases and a sialyltransferase were also tested, but only HS3ST1 and ST3GAL4 were detected in the abomasum and their transcription level did not change during infection." (PMID 21569362, 2011).
HS3ST1 also shares sentences with these, for which no sentence is quoted: glioma (3 papers); glioblastoma (2); hepatocellular carcinoma (2); Alzheimer disease (1); anaplastic astrocytoma (1); chronic kidney disease (1); invasive breast ductal carcinomas (1); oligodendroglioma (1); pancreatic adenocarcinoma (1); pancreatic ductal adenocarcinoma (1); renal carcinoma (1); triple-negative breast carcinoma (1).